EGFR (epidermal growth factor receptor)
Diseases named in the same sentence as EGFR in open-access papers (continued):
Sharing a sentence is not in itself a finding about the gene and the disease.
tumor (continued). "It was also obvious that CAFs derived from the AT (αSMA-low, SOX2-high, p16+) or BA (αSMA- and EGFR-high and low SOX2/TP63 ratio) mRNA subtypes could support the growth of both types of tumour cells (primary-tumour ones as well as metastatic-derived ones), while CL and ME CAFs were more specific." (PMID 35565415, 2022). "Therefore, targeting both the EGFR pathway and ERBB family receptors may be necessary to achieve a vigorous anti-tumor response." (PMID 35954407, 2022). "However, only double targeting of EGFR and ERBB2 led to durable tumor regression." (PMID 35582524, 2022). "We co-encapsulated rapamycin and gefitinib into chitosan nanoparticles (NP) at a reasonable ratio to tune the cellular uptake; we then coated the NP with anti-EGFR aptamers to deliver drugs preferentially to the tumor site and to minimize non-targeted delivery." (PMID 35887373, 2022). "Furthermore, the crosstalk between the EGFR and programmed cell death protein 1/programmed cell death ligand 1 (PD-1/PD-L1) is observed in the NSCLC, which downregulates T cell signaling and helps the tumor evade immune surveillance." (PMID 36547898, 2022). "The third-generation of CAR-T cells with an scFv region of anti-EGFR antibodies showed antitumor and cytotoxic effects in TNBC cell cultures (HS578T, MDA-MB-231, MDA-MB-468) and TNBC cell lines derived xenograft mouse models through mechanisms of enhancing cytokine release and tumor lysis." (PMID 35414783, 2022). "Furthermore, in vitro experiments suggested that ARID1A knockdown (ARID1A-KD) activates the EGFR/PI3K/Akt/mTOR pathway and inhibits tumor cell autophagy, which attenuates inhibition of the Rig-I-like receptor pathway and production of type I interferon (IFN) in EGFR-mutant LUAD cells." (PMID 36229854, 2022). "Indeed, the inhibition of tumor cell growth by STAP-2 knockdown occurs under EGFR-activated conditions but not under EGFR-inactivated conditions." (PMID 36010693, 2022). "Ep4, which was derived from a P51 tumor pathologically assigned to the luminal type because of their weakly positive progesterone receptor (PR) without ER expression (Allred scores: ER, 0; PR, 3), had low VIM activity but the high activity of EGFR and relatively low activity of luminal keratins." (PMID 35676392, 2022). "In addition, the inhibition of some of these markers, using Ang1 analogs, inhibitors of EGFR, TRAF6, or combined inhibitors of EGFR and IGF-IR, may lead to a decrease in tumor size." (PMID 35956111, 2022). "Our findings suggested that nuclear EGFR/NONO positive feedback loop facilitates tumor malignant progression and NONO might be a promising therapeutic target for TNBC with high expression of nuclear EGFR." (PMID 35013116, 2022). "Although the presence of BRAF mutations does not contraindicate the use of anti-EGFR antibodies, patients with BRAF mutant cancer have a poor prognosis due to the relative resistance of this tumor type to chemotherapy and often receive more aggressive therapeutic regimens." (PMID 35205799, 2022). "Thus, EGFR-mutant NSCLC may have a distinct TME and identifying key factors involved in anti-tumor responses will provide powerful predictive biomarkers for immunotherapy." (PMID 35990690, 2022). "Therefore, low doses of unconjugated DD1 or DFc could be suitable to saturate EGFR binding sites of normal tissues 6–24 h before injecting any anti-EGFR MMAE conjugate and push its anti-tumor efficacy." (PMID 35269611, 2022). "Moreover, in other cancer types, anti-CD47 blockade has been demonstrated to enhance macrophage ADCP of tumour cells in response to TAA-targeting IgG mAbs, including Trastuzumab, anti-CD20 IgG1 Rituximab (Rituxan), and anti-epidermal growth factor receptor (EGFR) IgG1 Cetuximab (Erbitux)." (PMID 35020853, 2022). "Importantly, the xenograft model showed that both the non-target and EGFR-targeted liposomes significantly inhibited tumor growth compared to free CPT-11." (PMID 35918704, 2022).
tumor (continued). "Researchers have designed EGFR-targeting CARs that lead to inactive PD-1 in the non-cancerous environment but are selectively activated through proteolytic cleavage by protease present in the tumor environment." (PMID 35326556, 2022). "In the first-line setting, the choice between anti-angiogenic and anti-epidermal growth factor receptor (EGFR) agents is driven by RAS and BRAF mutational status and tumour sidedness; in contrast, no predictive factors have been identified to favour oxaliplatin over irinotecan or vice versa." (PMID 36230995, 2022). "As stated in Methods, all patients with available tumor tissue sample were screened for mutations in the entire series of additional candidate genes (KRAS, ALK, BRAF, MET) regardless of the positive or negative result of the EGFR mutation testing." (PMID 35012520, 2022). "Finally, it may also be possible to incorporate such reduced sensitivity EGFR-sdCARs in multi-antigen targeting CAR strategy that will ultimately recognize and lyse tumor cells in more selective fashion." (PMID 35935988, 2022). "For example, cytokines such as IL-8, which are consistently elevated in all cell lines regardless of EGFR-TKI treatment, may have caused additional signaling changes in persistent tumor cells." (PMID 36612121, 2022). "With high expression levels of PDL-1 and EGFR on the cell surface plus both BRAF V600E and KRAS G13D existing within its genome, the A375 KRAS G13D mutant isogenic line is an ideal model suited for future studies focused on the tumor microenvironment and integrated combination therapy strategies." (PMID 36358868, 2022). "Moreover, avoiding ‘on-target/off-tumor’ binding to PD-L1 on nonmalignant cells, EGFR×PD-L1 bispecific antibody was developed for EGFR+ tumors." (PMID 35062949, 2022). "Considering that EGFR and other tyrosine kinase receptors of the ErbB/HER family are upregulated in nearly half of all human cancers, magnetic switches may be considered safe and powerful vehicles for anti-tumor therapy." (PMID 36232435, 2022). "For example, activity changes in oncogenic pathways often modulate the tumor microenvironment, and we observed a strong correlation between promoter or enhancer methylation and target gene expression for the MAPK pathway (EGFR) and WNT-beta-catenin pathways (CTNNB1, WNT3A and WNT7B)." (PMID 34987166, 2022). "In addition, tumor antigen, such as EGFR, is widely expressed in normal, non-neoplastic tissues, and its use as a target antigen can lead to severe on-target, off-tumor immunotoxicity." (PMID 36076251, 2022). "Notably, cemiplimab monotherapy is already indicated for use (in the United States and in the European Union) as a first-line therapy for adult patients with NSCLC and high PD-L1 expression (≥50% of tumour cells), but without EGFR, ALK, or ROS1 aberrations." (PMID 35328510, 2022). "This method, however, relies on ultrasound irradiation and the presence of EGFR on tumor cells, which might not be translatable to real-world clinical routines and possibilities." (PMID 35214121, 2022). "In a xenograft model, treatment with the EGFR-targeted doxorubicin/photosensitizer-loaded nanoparticles, followed by NIR laser irradiation, led to an impressive result: complete regression of the tumor, at least for the duration of the experimental evaluation (14 days)." (PMID 35626078, 2022). "Among CD8+ T cells, M1 (CD68+HLA-DR+) tumor-associated macrophages (TAMs), M2 TAMs (CD68+HLA-DR-), CD56bright NK cells and CD56dim NK cells, less CD8+ T cell infiltration was found in the EGFR mutation group than in the group without EGFR mutation (p<0.05)." (PMID 35265073, 2022). "No tumor with EGFR or ALK alterations demonstrated radiographical response or MPR." (PMID 36097216, 2022). "Moreover, we also found the expression of short ChAT isoform at mRNA and protein levels in tumor and adjacent normal lung tissues derived from NSCLC patients with or without EGFR mutation." (PMID 36048538, 2022).
tumor (continued). "Mechanisms in different contexts include reactivation of EGFR signalling following MAPK pathway blockade, reactivation of MAPK pathway itself, activation of parallel pathways (e.g. HER2, MET or PI3K) or activation of focal adhesion kinase (FAK) to promote tumour cell survival." (PMID 34856074, 2022). "The tumor mass in the xenograft models will be examined for apoptosis alternation such as caspase enzyme activity or DNA repair enzymes (such as Uracil-DNA glycosylase) and tested for the interaction of HPV oncoprotein and EGFR nuclear trafficking-related factors such as cyclin D1." (PMID 36358752, 2022). "Thus, patients who are ineligible for combination chemotherapy do not benefit from anti-tumor activity of anti-EGFR antibodies." (PMID 35897060, 2022). "On the basis of our observations that blocking EGFR signalling in oncogene-driven NSCLC alters the TME towards a proinflammatory status, thus promoting an enhanced immune response, we next examined tumour growth rates by analysing target lesion size to assess tumour response." (PMID 36010935, 2022). "The main reason is that some tumor patients are not sensitive to EGFR-targeted therapy." (PMID 35706930, 2022). "However, cetuximab treatment substantially abrogated Src activation in EGFR-high tumor tissues but did not affect Src activation in EGFR-low tumor tissues." (PMID 32989241, 2021). "While researchers have sought to disrupt TNBC tumor growth using EGFR-blocking antibodies or other approaches for EGFR degradation, these treatments have failed to achieve beneficial outcomes in many TNBC patients, instead exhibiting a high degree of response heterogeneity." (PMID 34298600, 2021). "Secondly, although EGFR-TKI monotherapy could reduce AEs, considering tumor heterogeneity and the efficacy of other treatment regimens, including chemotherapy and radiotherapy, different combination therapies should also be further investigated for assessing the optimal adjuvant therapy." (PMID 33842322, 2021). "MDA-MD-231 tumor growth arrest did not initially depend on ER or EGFR inhibition." (PMID 34638492, 2021). "The data published to date suggests that the first-line immunotherapy in monotherapy strategy has become the new standard of care in locally advanced and metastatic NSCLC patients with high PD-L1 expression levels and no EGFR and ALK genomic tumor aberrations targetable mutations." (PMID 34640601, 2021). "Specifically, tumor cells express high levels of HSF1 via a variety of methods, for example, inhibiting the ubiquitinated degradation of HSF1, reducing the expression of molecules that compete with HSF1 and stimulating HSF1 activation-related pathways (such as EGFR mediated MAPK pathway)." (PMID 33422093, 2021). "The limited efficacy of immunotherapy single-agent in EGFR mutant NSCLC was already recognized in the advanced setting, probably related to the low T-cell infiltration and tumor mutational burden and the intrinsic lack of immunogenicity of the oncogene-addicted disease." (PMID 34685665, 2021). "The best samples to be analyzed at progression under third-generation EGFR-TKIs or after negative analysis of cfDNA under first–second-generation EGFR-TKI remain tumor tissues; even though some progress was made for cfDNA analysis, it is generally not accessible in clinical practice." (PMID 34638411, 2021).
tumor (continued). "For further evaluating whether the interactions of MYOF with EGFR and EPHA2 are shared across tumor types, we analyzed MYOF co-expression with the members of common cell membrane receptor kinase (RTK) family from the proteomic data of 375 cancer cell lines from 22 lineages in CCLE." (PMID 34178975, 2021). "Although the sample in Case 1 had enough tumor content, Case 1 did not respond to EGFR‐TKI." (PMID 33314600, 2021). "In addition, EGFR and HER2/Neu staining were both moderately positive and consistent with the results of gene sequencing, which indicated that there was no EGFR or HER2 amplification in the tumor." (PMID 34162944, 2021). "Compelling experimental and clinical evidence also demonstrated that EGFR signaling actively regulates the tumor immune microenvironment and that EGFR inhibition prompts not only an increase in TILs and expression of immune checkpoints, but also serves as a promising immunotherapy sensitizer." (PMID 33800421, 2021). "This is a novel trial in evaluating the clinical benefits of continuing EGFR inhibition versus VEGF inhibition in treating wild-type KRAS, NRAS and BRAF V600E mCRC tumors with second-line cetuximab or bevacizumab plus chemotherapy crossover after tumor progression to first-line cetuximab regimen." (PMID 34335943, 2021). "Even if EGFR is not expressed in this tumor, the question arises, whether downstream signaling pathways are still operative, which might then not be linked to EGFR but to other signaling molecules." (PMID 33313992, 2021). "Mouse tumor models expressing a β4 mutant lacking its “signaling domain” (β41355T) have been instrumental in demonstrating its critical role in tumorigenesis and tumor-induced angiogenesis that depends on EGFR, HER2 or c-MET." (PMID 34778093, 2021). "However, even if tumor shrinkage is achieved, most patients become resistant to EGFR-TKIs and relapse; hence, EGFR-TKIs do not achieve a radical cure." (PMID 34831415, 2021). "In some ERMS (but not all), EGFR can contribute to tumor growth." (PMID 34359977, 2021). "On the other hand, by fusing the CD16-specific VHH to VHHs against other tumor targets of interest, tumors negative for EGFR could also be targeted." (PMID 34771609, 2021). "In vivo, cinobufagin blocked EGFR signaling, inhibited cell proliferation, and elicited apoptosis, thereby suppressing tumor growth in both subcutaneous and intracranial U87MG-EGFR xenograft mouse models and increasing the median survival of nude mice bearing intracranial U87MG-EGFR tumors." (PMID 34925034, 2021). "An alternative explanation for the resistance to such ICI treatments might be related to the discussed lack of tumour infiltrating lymphocytes (TILs) in tumours that overexpress mutant forms of the EGFR." (PMID 35052732, 2021). "The nanostructure could block EGFR signal transduction and exhibited excellent selectivity for cells with elevated EGFR expression, which exhibited significant anti-tumor activity without obvious systemic toxicity." (PMID 34876145, 2021). "Furthermore, EGFR aptamers-functionalized micelles proved more effective compared to non-targeted micelles both in vitro and in tumor xenograft-bearing mice." (PMID 34452081, 2021). "Binding of EGFL7 to EGFR enhanced cell migration of hepatocellular carcinoma cells and increased intrahepatic and pulmonary metastases in murine liver cancer models but did not alter tumor cell proliferation." (PMID 33804387, 2021). "Importantly, findings from this study supported using blood tests to monitor the emergence of MET amplification in patients undergoing anti-EGFR therapies, as the amplification of the MET locus has been present in circulating tumor DNA before any clinical evidence of relapse." (PMID 34326875, 2021).
tumor (continued). "In another phase I/II trial, a combination of everolimus and gefitinib [epidermal growth factor receptor (EGFR) inhibitors] caused a rapid increase in PSA level, though the standardized uptake value was transient, thus it was not able to affect tumor growth significantly." (PMID 34452154, 2021). "Anti-EGFR/VEGFR2 BsAb showed enhanced anti-tumor activities via multiple mechanisms of action in both in vitro and in vivo models of TNBC, suggesting that co-targeting of EGFR and VEGFR2 with this BsAb can result in synergistic anti-tumor activities than single agent treatment." (PMID 33804477, 2021). "The EGFR downstream signaling cascades themselves have been shown to regulate PD-L1 expression in different tumor entities including HPV negative HNSCC tumor specimens that rely on a tumor-intrinsic, EGFR-directed PD-L1 expression for immune evasion." (PMID 33718186, 2021). "Concurrent mutations in EGFR or ERBB2 and KRAS are not selected for and may be considered redundant in tumor cells, thus selective pressures may account for the mutual exclusivity of EGFR/ERBB2 and KRAS." (PMID 34204917, 2021). "The rationale for the combination of EGFR inhibitors with RT is mainly based on the role of EGFR in driving the disease rather than on how the two modalities might work together to kill the tumor." (PMID 34733787, 2021). "For patients who receive EGFR-TKI treatment, a certain regularity of tumour volume shrinkage may be deduced, or 60 days may be the time to carry out radiotherapy by means of mathematical modelling, but an individualized analysis was not performed, and the actual pattern of TVC was not examined." (PMID 34631535, 2021). "BRAF mutant tumours are associated with poorer prognosis; in particular, the BRAFV600E mutation is associated with a lack of response to anti-EGFR therapies (such as cetuximab) if not treated simultaneously with an anti-BRAFV600E treatment (such as encorafenib)." (PMID 34945008, 2021). "Despite the EphA3-related molecular alterations associated with IL-26 alone, treatment with IL-26 alone did not alter TNBC growth; rather, the effect of IL-26 on TNBC tumor growth was seen in the setting of EGFR-TKI exposure with an increased ER stress response." (PMID 34021125, 2021). "In addition, the supernatant cell‐free DNA (cfDNA) of the sputum is verified to be suitable for EGFR sensitive mutation detection for treatment‐naïve patients with advanced NSCLC, and especially valuable when tumor tissue is not available." (PMID 33932095, 2021). "What causes the difference between EGFR mutant and non-mutant tumors and how the tumor biology changes after EGFR inhibitor treatment failure remain largely unknown." (PMID 33787673, 2021). "However, a role for CPAP as a tumor suppressor in regulating EGFR homeostasis and signaling, and EMT is not known." (PMID 33889303, 2021). "Although targeted therapy using anti-EGFR antibodies (cetuximab, and panitumumab) was moderately effective in PDAC, their employment as targeting vehicles for NIR-fluorescence imaging has allowed clear tumor delineation in both preclinical and clinical settings." (PMID 34885196, 2021). "RIT may also prove more effective than “naked” anti-EGFR mAbs, since it does not rely on inhibiting tumour growth signaling, but rather on inflicting lethal DNA damage." (PMID 34383182, 2021).